LEF1 (lymphoid enhancer binding factor 1)
Diseases named in the same sentence as LEF1 in open-access papers (continued):
Sharing a sentence is not in itself a finding about the gene and the disease.
alopecia (3 papers, 2013 to 2023). Hair loss usually from the scalp. "Interestingly, Lef1 knock-out mice develop alopecia at an early age and transgenic mice expressing a dominant negative Lef1 in keratinocytes also show a phenotype that resembles that of Vdr−/− mice." (PMID 24202444, 2013).
astrocytomas (3 papers, 2018 to 2021). "A positive correlation was also found between the expression level of TCF4 and LEF1 compared to the astrocytoma grade." (PMID 30468298, 2019). "Both factors were found to be expressed in our total sample where the levels of both TCF1 and LEF1 expression increased with astrocytoma grades." (PMID 30468298, 2019). "Diffuse astrocytomas had significantly more cells with strong LEF1 expression as compared with pilocytic (P < 0.001) and anaplastic (P = 0.008), while anaplastic had significantly more cells with strong LEF1 expression than pilocytic (P = 0.008)." (PMID 30468298, 2019). "However, TCF1 and LEF1 were both significantly upregulated and increasing with astrocytoma grades (P = 0.001)." (PMID 30468298, 2019). "There was, however, a correlation between strong LEF1 expression and higher astrocytoma grades." (PMID 30394013, 2018). "However, strong LEF1 expression levels were significantly correlated with higher astrocytoma grades (Spearman’s rho 0.642, P = 0.006)." (PMID 30394013, 2018). "Moreover, the levels of both TCF1 and LEF1 expression increased with astrocytoma grades." (PMID 30468298, 2019).
Autoimmunity (3 papers, 2020 to 2023). The occurrence of an immune reaction against the organism's own cells or tissues. "TCF7 acts with LEF1 to control the maintenance and functional specification of Treg subsets to prevent autoimmunity." (PMID 36077273, 2022). "The wnt signalling pathway, including TCF-1 and LEF-1, can also modulate mature T cell function, including prolonging regulatory T cell (Treg) survival and therefore, potentially impacting on autoimmunity." (PMID 32835228, 2020).
chronic myeloid leukemia (3 papers, 2014 to 2024). "Intriguingly, the ability of Hh to crosstalk with Wnt is suggested by Sengupta and coworkers, who demonstrated that Hh signaling via Stat3 activation gives rise to the expression of Wnt3a, Lef1, Gli1–3, and other target genes in the chronic phase of chronic myeloid leukemia (CML)." (PMID 31552081, 2019). "Lymphoid enhancer factor-1 (LEF-1), a Wnt-mediating transcription factor important for cell survival and metastasis in cancer, is produced via IRES-directed translation, and its mRNA is frequently upregulated in malignancies, including chronic myeloid leukaemia (CML)." (PMID 25392452, 2014).
desmoid-type fibromatosis (3 papers, 2013 to 2025). "En bloc resection revealed desmoid-type fibromatosis composed of bland spindle cells in a collagenous stroma, with nuclear β-catenin and lymphoid enhancer–binding factor 1 (LEF1) positivity on immunohistochemistry." (PMID 41227209, 2025). "In this study, we focused on three common WNT-activated tumors, basal cell adenoma (BA), desmoid-type fibromatosis (DF), and pancreatic solid pseudopapillary neoplasm (SPN) to systematically evaluate the expression patterns of β-catenin and LEF1 and analyze their diagnostic value." (PMID 39881334, 2025). "The transcription regulation of matrilysin requires the LEF-1/TCF beta-catenin pathways and a correlation between beta-catenin widespread nuclear expression and MMP7 overexpression was reported in sporadic desmoid tumors." (PMID 24143235, 2013).
diabetes (3 papers, 2020 to 2024). "The C/C cells showed differential binding affinity compared to C/T cells in some previously identified TCF7L2 target genes that are involved in diabetes, such as ACSL5, ATM, AKT2, LEF1, and PDK4." (PMID 32651957, 2020). "In fact, in this study we also demonstrated that a downregulation of LEF-1 in T2D bone goes along with a downregulation of COL1A1, strengthen data of a reduced production of bone matrix most likely as the result of reduced osteoblasts synthetic activity in diabetes." (PMID 38598270, 2024). "Expedited levels of LEF-1 in tumors coupled with high glucose levels in diabetic individuals promoting the LEF1–β-catenin complex formation is highly likely to accelerate malignant transformations, hinting at the prominent role of Wnt signaling in diabetes and cancer." (PMID 39692821, 2024).
ectodermal dysplasia (3 papers, 2022 to 2024). "In addition, monoallelic and biallelic LEF1 variants have been proposed as causative factors for a putatively novel syndrome characterized by limb malformations and ectodermal dysplasia." (PMID 36294409, 2022). "In fact, mutations in LEF1 (MIM: 153245), which is a transcription factor downstream of the Wnt signaling, has been linked to ectodermal dysplasia, including one individual also affected by microcephaly." (PMID 39168120, 2024). "Ectodermal dysplasias (ED) is a family of genetic skin diseases in which the common clinical sign is hypertrichosis, and inactivation of Lef1 targeting in mice leads to complete blockage of ectodermal development." (PMID 35893063, 2022).
intestinal tumors (3 papers, 2011 to 2023). "Future studies should also address the metabolic and possible immune functions of Lef1 in intestinal tumors." (PMID 34788095, 2021). "As we were unable to test whether Lef1 deletion attenuated tumorigenesis in our mice, defining this will be a priority, particularly given that Lef1 ablation in a murine intestinal tumour model unexpectedly increased tumour development." (PMID 37589076, 2023).
lymph node metastasis (3 papers, 2018 to 2023). "In patients with NPC, 43.5% of the cases (170/391) showed positive expression of LEF1; additionally, LEF1 expression was associated with poor OS and several clinicopathological features (including lymph node metastasis and advanced clinical stage)." (PMID 32856045, 2020).
myelodysplastic syndrome (3 papers, 2015 to 2019). A clonal hematopoietic disorder characterized by dysplasia and ineffective hematopoiesis in one or more of the hematopoietic cell lines. "Conversely, in patients with myelodysplastic syndrome, advanced disease and poor prognosis were associated with downregulation of LEF-1, probably reflecting the impaired maturation of myeloid progenitors associated with loss of LEF-1 function." (PMID 25805670, 2015). "Moreover, an obvious downregulation of LEF1 has been associated with disease progression in myelodysplastic syndrome." (PMID 25942645, 2015).
myeloid leukaemia (3 papers, 2014 to 2025). "A survey of LEF1 expression in primary myelogenous leukaemias determined that LEF1 mRNA and other Wnt target genes (c-MYC) are increased in the final blast phase (BP) stages of chronic myeloid leukaemia (CML) compared with those from earlier, slower growing chronic phases (CPs)." (PMID 25392452, 2014). "Many of those genes inhibited by SID peptide treatment (CD44, TGFβR2, LEF1, TCF7L2, FGF2, FGF5, ID2, PIK3R3) are known as direct TGIF1 targets in myeloid leukemia or embryonic stem cells." (PMID 29179446, 2017).
Myeloma (3 papers, 2020 to 2024). "Additionally, the most activated TFs in each subgroup within the M1-M5 modules were identified as follows: MAF in the C0 IGLL5+ Myeloma Cells subgroup, LEF1 in the C1 IGHG4+ Myeloma Cells subgroup, TCF12 in the C2 MALAT1+ Myeloma Cells subgroup, and CREB5 in the C3 IGHG1+ Myeloma Cells subgroup." (PMID 39281682, 2024).
myocardial infarction (3 papers, 2021 to 2025). Gross necrosis of the myocardium, as a result of interruption of the blood supply to the area, as in coronary thrombosis. "At present, a large number of studies have demonstrated that LEF1 is linked to many cardiovascular diseases through the Wnt/β‐catenin signalling pathway, such as hypertrophic cardiomyopathy, myocardial infarction and myocardial fibrosis." (PMID 41208012, 2025).
neutropenia (3 papers, 2010 to 2025). A decrease in the number of neutrophils found in the blood. "The decrease in transcription factor expression is difficult to interpret both because LEF1 gene is normal and because LEF1 expression is depending of type of congenital neutropenia." (PMID 21595885, 2011). "SPINK5 is related to a skin disorder and is consistent with the clinical picture of Pt#5, who is affected with psoriasis; the possible connection with neutropenia might be explained by the expected reduced expression of LEF1, which in turn deregulates lymphocyte activity." (PMID 40725177, 2025).
renal cell carcinoma (3 papers, 2020 to 2022). "Of note, in previous studies, TGFB1 has been found to enhance proliferative and metastatic potential by upregulating lymphoid enhancer-binding factor 1 and integrin αMβ2 in human renal cell carcinoma, and PVRL2 has been found to be induced in cancer and to suppress CD8+ T lymphocyte function." (PMID 35860689, 2022). "The combination of the DNA methyltransferase inhibitor 5-aza-2′-deoxycytidine (DAC) and the chemotherapeutic agent paclitaxel was found to enhance LEF1 suppression and attenuate tumor growth in renal cell carcinoma (RCC) cells with high levels of LEF1 expression." (PMID 32933177, 2020).
sarcoidosis (3 papers, 2022 to 2025). Sarcoidosis is a multisystemic disorder of unknown cause characterized by the formation of immune granulomas in involved organs. "In a prior gene co-expression analyses of peripheral blood and cutaneous lesions we noted that transcription factors, such as ETS1, IKZF3, LEF1, MYC, RORA, and SPI1 (PU.1), may be central players in aberrant processes associated with sarcoidosis." (PMID 36311769, 2022). "Therefore, the downregulation of LEF1 contributed to the diagnosis of sarcoidosis in our study." (PMID 36405616, 2022). "Additionally, CD4+ T cells from sarcoidosis patients exhibited increased PRDM1 and GATA3 expression, while naive markers SELL, TCF7 and LEF1 were reduced in sarcoidosis and active TU compared with healthy donors." (PMID 40469525, 2025).
T-cell leukemia (3 papers, 2020 to 2022). A malignant disease of the T-lymphocytes in the bone marrow, thymus, and/or blood. "In an adult cohort of T-ALL patients, high LEF1 expression was associated with increased expression of the oncogenes encoding c-MYC and CYCLIN D1 suggesting that LEF1 is positively associated with T cell leukemia." (PMID 35514954, 2022). "To gain insight into the role of LEF1 in T-ALL we investigated its requirement in the generation of E2a-/- T cell leukemias." (PMID 35371057, 2022). "Here, we investigate the potential gene targets of LEF1 in the Jurkat human T-cell leukemia cell line." (PMID 32586085, 2020). "Our results suggest that DHRS2 is one of the tumor suppressor targets of LEF1 in the Jurkat human T-cell leukemia cell line." (PMID 32586085, 2020).
T-cell lymphoma (3 papers, 2020 to 2025). "The β-catenin-LINC00183-miR-371b-5p-Smad2/LEF1 axis promotes T-cell lymphoma progression and chemoresistance, as seen in T-cell lymphoblastic lymphoma." (PMID 40024178, 2025). "In addition, Lef1 has been reported as a transcriptional target of NOTCH1 in T-cell lymphomas and to accelerate Notch1-induced lymphomagenesis in mice." (PMID 31586130, 2020).
acute leukemia (2 papers, 2015 to 2017). A clonal (malignant) hematopoietic disorder with an acute onset, affecting the bone marrow and the peripheral blood. "Our findings underscore the pro-survival and oncogenic effect of LEF1 in acute leukemia particularly B-ALL, revealing high LEF1 expression may link to high-risk ALL." (PMID 25942645, 2015).
Anxiety (2 papers, 2017 to 2022). Intense feelings of nervousness, tension, or panic often arise in response to interpersonal stresses. "Surprisingly, Ingenuity Pathway Analysis (IPA) identified Lef1-dependent genes as being most highly associated with anxiety and depressive disorder." (PMID 28837622, 2017). "Interestingly, many Lef1-dependent genes in zebrafish encoding components of anxiety-mediating transmitter pathways, such as GABA, 5-HT, and CRH, have a conserved function in Drosophila anxiety-like behavior." (PMID 28837622, 2017). "Here, we show that Lef1 is required for the differentiation of hypothalamic neurons that inhibit anxiety in both zebrafish and mice, but through divergent molecular and cellular mechanisms in the 2 species." (PMID 28837622, 2017). "Gene knockout experiments in mouse and zebrafish show that the molecular signal Wnt acts through the transcription factor Lef1 to inhibit anxiety in both species." (PMID 28837622, 2017). "The body growth and anxiety phenotypes in lef1 mutants could be explained by reduced expression of multiple hypothalamic genes including crhbp, which encodes a corticotropin-releasing hormone (CRH) inhibitor." (PMID 28837622, 2017). "Likewise, our data do not conclusively prove that crhbp+ neurons, or indeed any individual Lef1-dependent neuronal populations, mediate the effect of Lef1 on anxiety." (PMID 28837622, 2017). "However, both male and female Lef1CKO mice gained weight more slowly after weaning, similar to the phenotype we observed in zebrafish lef1 mutants, and again consistent with elevated anxiety." (PMID 28837622, 2017). "Together these results suggested that lef1 mutants might have an anxiety-related behavioral phenotype." (PMID 28837622, 2017). "Together, these results suggest a conserved role of hypothalamic Lef1 in inhibiting anxiety." (PMID 28837622, 2017). "We found that lef1 mutant larvae had a longer latency to enter the upper half of a novel tank and spent less overall time in this zone during the initial exploration phase, consistent with elevated anxiety." (PMID 28837622, 2017). "Notably, lef1 mutants travelled less distance during this phase, partially due to more frequent freezing behavior as indicated by increased time in immobility, and again consistent with elevated anxiety." (PMID 28837622, 2017). "While we cannot rule out the possibility that our RNA-seq analysis of the mouse hypothalamus lacked the sensitivity to identify other conserved Lef1-dependent genes, it is clear that the identity of Lef1-dependent neurons relevant for anxiety differs between zebrafish and mice." (PMID 28837622, 2017). "Further, the Wnt/β-catenin effector Lef1 is required for the development of the hypothalamus and differentiation of anxiolytic hypothalamic neurons in both zebrafish and mice, which also displayed increased anxiety in zebrafish in the absence of Wnt/β-catenin signaling." (PMID 35996200, 2022). "Importantly, lef1 mutants no longer displayed anxiety-related behavior after the exploration phase." (PMID 28837622, 2017).
atherosclerosis (2 papers, 2020 to 2023). A disease characterized by the build-up of fatty material and calcium deposition in the arterial wall resulting in partial or complete occlusion of the arterial lumen. "Similarly, the expression levels of CD28, TRAT1, TRAV13-1, and LEF1 were related to smoking and smoking-related atherosclerosis." (PMID 37762221, 2023).
basal cell carcinoma (2 papers, 2017 to 2023). A carcinoma involving the basal cells. "KEGG enrichment analysis indicated upregulated DEGs were involved in Renin-angiotensin system (e.g., Agt, angiotensinogen) and Wnt signaling pathway (e.g., Dkk1), while downregulated DEGs participated in Basal cell carcinoma (e.g., Lef1)." (PMID 29121993, 2017). "As a result, 24 KEGG pathways were enriched for upregulated DEGs, including Renin-angiotensin system (e.g., Agt, angiotensinogen), Renin secretion (e.g., Agt), and Wnt signaling pathway (e.g., Dkk1), while 16 pathways were for downregulated DEGs, including basal cell carcinoma (e.g., Lef1)." (PMID 29121993, 2017). "The regulatory network also showed that DEGs including LEF1, FZD3, SMAD3, and BMP4 were important regulators of the Wnt signaling, basal cell carcinoma, and Hippo signaling pathways." (PMID 36979137, 2023).
cardiac hypertrophy (2 papers, 2019 to 2023). "A recent study has shown that PM2.5 exposure can induce cardiac hypertrophy via circRNA_0001859, which suppressed miR-29b-3p, resulting in an enhanced Ctnnb1 level and activated the downstream pathway molecules like LEF1/IGF-2R." (PMID 37626874, 2023). "As such it is worthwhile to investigate the precise mechanisms of interplay between β-catenin/LEF1 signaling and Ang-II induced cardiac hypertrophy response." (PMID 31480672, 2019). "This study deciphered that β-catenin gets abnormally induced under hypertensive conditions which co-activated LEF1 and lead to cardiac hypertrophy changes by up-regulating the IGF-IIR signaling pathway." (PMID 31480672, 2019). "Through this study, we examined the impact of β-catenin in Ang-II induced hypertrophy responses and demonstrated that IGF-IIR expression could be regulated by β-catenin/LEF1 leading to pathological cardiac hypertrophy signaling." (PMID 31480672, 2019). "We identified putative LEF1 consensus binding site on IGF-IIR promoter that could be regulated by β-catenin/LEF1 which in turn modulate the expression of cardiac hypertrophy agents." (PMID 31480672, 2019). "Protein expression analysis revealed Ang-II induced cardiac hypertrophy agents such as IGF-IIR, Gαq, and PKCα, were downregulated upon silencing of either β-catenin, or LEF1, or both." (PMID 31480672, 2019).
cervical cancer (2 papers, 2024 to 2025). A primary or metastatic malignant neoplasm involving the cervix. "Notable findings include CD70, FANCD2, PFKP, MORN3, and LEF1, which exhibited strong causal associations and potential relevance in cervical cancer pathogenesis." (PMID 40817807, 2025).
ductal adenocarcinomas (2 papers, 2020 to 2025). "A combined IHC panel of beta catenin, LEF1 and TFE3 resulted in a sensitivity and specificity of 100 and 91.9% in distinguishing SPNs from ductal adenocarcinomas and Pan NETs." (PMID 33298094, 2020).
endometrial tumors (2 papers, 2012 to 2025). "Our generation of mouse endometrial tumors via uterine NMU injections enabled us to confirm that high Lef1 expression is associated with uterine tumors, and to characterize Lef1 location in this context." (PMID 22792274, 2012). "Finally, Lef1 is overexpressed in human and mouse endometrial tumors, consistent with it playing a role in gland proliferation." (PMID 22792274, 2012). "We also noted that Lef1 was expressed at higher levels within normal proliferative endometrium and in all endometrial tumors (regardless of histologic subtype) than in inactive endometrium." (PMID 22792274, 2012). "Immunostaining of these tissues shows that Lef1 protein is expressed in normal proliferative tissue and endometrial tumors, but not in inactive postmenopausal tissue." (PMID 22792274, 2012).
essential hypertension (2 papers, 2019 to 2023). Hypertension that presents without an identifiable cause. "When compared to controls, β-catenin protein level was increased in the nuclear fraction of hypertension rat cardiac tissue and directly bound to LEF1." (PMID 31480672, 2019).
Ewing sarcoma (2 papers, 2019). A small round cell tumor that lacks morphologic, immunohistochemical, and electron microscopic evidence of neuroectodermal differentiation. "Inversely, some studies have shown that EWS/FLI1 inhibits β-catenin dependent transcription through a direct interaction between EWS/FLI1 and the transcription factor LEF1, inhibiting the interaction between β-catenin and LEF1 in Ewing sarcoma-cell lines." (PMID 31370265, 2019). "In this study, we showed that APCDD1 knockdown increased the expression of CDC25A, LRP6, LEF1 and NKD1, which are confirmed targets of the canonical Wnt pathway in Ewing sarcoma, implying that APCDD1 might act as a Wnt inhibitor in this cancer." (PMID 30496486, 2019).